SF3B1 (splicing factor 3b subunit 1)
Diseases named in the same sentence as SF3B1 in open-access papers (continued):
Sharing a sentence is not in itself a finding about the gene and the disease.
uveal melanoma (continued). "Major genetic drivers identified in uveal melanoma include early events activating GNAQ (at 9q21) or GNA11 (at 19p13) and later events involving EIF1AX (at Xp22) or SF3B1 (at 2q33) or BAP1 (at 3p21)." (PMID 37761808, 2023). "To date, the occurrence and development of eye diseases have been primarily attributed to specific gene mutations, such as RB1 for retinoblastoma and GNAQ, GNA11, EIF1AX, SF3B1, BAP1, and PLCB4 for uveal melanoma." (PMID 27043545, 2016). "Some cases presented with mutations usually linked to uveal melanomas (GNAQ, GNA11, SF3B1, BAP1), but these mutations did not co-occur, suggesting a different tumorigenesis process than in UM." (PMID 34359736, 2021). "Sequencing of SF3B1 and EIF1AX in ten uveal melanomas with disomy 3 who developed metastases showed that none of them displayed EIF1AX mutations, while 30% harbored a mutation in SF3B1." (PMID 29156643, 2017). "In summary, this is the first meta-analysis of driver mutations in uveal melanoma, showing that BAP1 mutations are linked to an increased risk of metastatic disease in uveal melanoma, while no such association was observed with GNAQ/GNA11 and SF3B1 mutations." (PMID 39061150, 2024).
chronic lymphocytic leukemia (70 papers, 2013 to 2025). "RNA splicing factor SF3B1 is one of the most recurrently mutated genes in chronic lymphocytic leukemia (CLL) and frequently co-occurs with chromosome 13q deletion [del(13q)]." (PMID 40694421, 2025). "Findings in this work were also evaluated in other independent cohorts with SF3B1 mutation occurrences, such as chronic lymphocytic leukemia (CLL)." (PMID 40158006, 2025). "We first studied a patient with chronic lymphocytic leukemia (CLL) with a late-acquired SF3B1-K700E mutation." (PMID 40877435, 2025). "SF3B1 mutations have also been detected in chronic lymphocytic leukemia (CLL), in which they are associated with potential alternative splicing events associated with anti-apoptotic functions." (PMID 36979496, 2023). "SF3B1 is mutated in the early stage of myeloid malignancies, whereas SF3B1 mutations in chronic lymphocytic leukemia (CLL) are most commonly subclonal and enriched in more advanced and aggressive disease." (PMID 37342192, 2023). "Selected enriched Gene Ontology terms (enrichGO R package) for biological processes in genes displaying differentially spliced events in SF3B1-mutated chronic lymphocytic leukemia patient samples and SF3B1K700E MEC1 cell lines." (PMID 37562845, 2023). "For example, the mutation of SF3B1 is highly related with several cancers including chronic lymphocytic leukemia (CLL), cutaneous melanomas, and uveal melanomas." (PMID 35327956, 2022). "Commonly differentially spliced mRNAs have been associated with SF3B1 mutations across tumour types including UV, chronic lymphocytic leukaemia, pancreatic cancer and breast cancer." (PMID 29848666, 2018). "SF3B1 mutations lead to mistakes in the splicing of some specific transcripts that affect the pathogenesis of chronic lymphocytic leukemia." (PMID 29050251, 2017). "Alterations in SF3B1 were initially discovered in myelodysplastic syndromes (MDSs) and chronic lymphocytic leukemia (CLL), together with other mutations of splicing factors, such as U2AF1, SRSF2 and ZRSR2 (refs 1, 2, 3)." (PMID 26842708, 2016). "In lymphocytes of patients with chronic lymphocytic leukemia, mutations in the gene encoding the splicing factor SF3B1 are more frequent after treatment, suggesting a chemotherapy-driven clonal selection for cells being affected in splicing." (PMID 25884497, 2015). "Using transcriptome sequencing data from chronic lymphocytic leukemia, breast cancer and uveal melanoma tumor samples, we show that hundreds of cryptic 3’ splice sites (3’SSs) are used in cancers with SF3B1 mutations." (PMID 25768983, 2015). "Moreover, we discovered that the SF3B1 mutation can cause the loss of Y chromosome in chronic lymphocytic leukemia." (PMID 39194178, 2024). "Inhibition of SF3B1 was associated with an increase in broad intron retention (IR) on most transcripts, suggesting that IR can be used as a marker of spliceosome inhibition in chronic lymphocytic leukemia (CLL) cells." (PMID 38846999, 2024). "Furthermore, SF3B1 is mutated in 10–15% of patients with chronic lymphocytic leukemia, highlighting the importance of understanding the role of SF3B1 in disease pathogenesis." (PMID 37511171, 2023). "In the SF3B1-mutated (SF3B1m) cancer patient samples including chronic lymphocytic leukemia, breast cancer, and melanoma, the mutations are between Y623 and G742, within the HEAT domain, which is required for interaction with the ATPase Prp5 and branch site selection." (PMID 30693020, 2018). "SF3B1 mutations are recurrent in chronic lymphocytic leukemia (CLL), particularly enriched in clinically aggressive stereotyped subset #2." (PMID 39261602, 2024). "Recurrent SF3B1 mutations have been reported in various cancer types, including chronic lymphocytic leukemia (CLL), and shown to induce altered splicing by alternative branch point usage or cryptic 3′ splice site selection." (PMID 39261602, 2024).
chronic lymphocytic leukemia (continued). "Mutations in SF3B1 are observed in 15% of patients with chronic lymphocytic leukemia (CLL) and are associated with poor prognosis, but their pathogenic mechanisms remain poorly understood." (PMID 37562845, 2023). "SF3B1 mutations are also found in 20% of MDS cases, in which a strong enrichment is found in MDS with ring sideroblasts, 15% of chronic lymphocytic leukemias and 6% of chronic myelomonocytic leukemia." (PMID 38517966, 2024). "For instance, lesions in Splicing factor 3B1 (SF3B1) occur in 5–17% of chronic lymphocytic leukemia (CLL) and in up to 46% of chronic myelomonocytic leukemia (CMML) patients, respectively, and are implicated in worse prognosis." (PMID 34356101, 2021). "Several studies indicated alterations in various signaling pathways in SF3B1-mutated cells, including an impaired DNA damage response (DDR) in chronic lymphocytic leukemia (CLL)." (PMID 33585229, 2020). "Mutations of the anti-apoptotic gene BIRC3 and splicing factor SF3B1 have correlated with fludarabine refractoriness in chronic lymphocytic leukemia/small lymphocytic lymphoma." (PMID 32197371, 2020). "When used in combination with BCL-2 inhibitors, these SF3B1 inhibitors have been demonstrated to induce apoptosis in small lung cancer cells, chronic lymphocytic leukemia cells and head and neck cancer cells." (PMID 28884683, 2017). "Importantly, the clinical relevance of this finding is underscored by the observation that low UBA7 gene expression was associated with poor overall survival in chronic lymphocytic leukemia (CLL), another hematological malignancy with frequent SF3B1 mutations." (PMID 40158006, 2025). "Similarly, the anti-proliferative potential of Spliceostatin A corresponding to the inhibition of the splicing process or spliceosome complex (SF3B1) has been observed in breast cancer (mutant cell lines), cervical cancers and chronic lymphocytic leukemia." (PMID 37483794, 2023). "For instance, SF3B1, SRSF1, U2AF65, and CELF4 are often mutated in chronic lymphocytic leukemia." (PMID 27287018, 2016). "In patients with chronic lymphocytic leukemia (CLL), SF3B1 gene alterations occur in approximately 10–14% of cases." (PMID 40158006, 2025). "Moreover, SF3B1 mutations also occur frequently in non-myeloid neoplasms such as chronic lymphocytic leukemia/small lymphocytic lymphoma, and have been associated with resistance to fludarabine therapy and poor clinical outcomes." (PMID 36671709, 2022). "For example, exome-sequencing studies found that SF3B1 was mutated in 10–15% of patients with chronic lymphocytic leukemia, while other spliceosome genes (e.g. SRSF1, SRSF7 and U2AF65) were mutated at lower (but still detectable) frequencies in chronic lymphocytic leukemia patients." (PMID 26498691, 2015). "In chronic lymphocytic leukemia (CLL), RPL32 expression can be used to predict SF3B1 expression, the major recurrent mutant gene in CLL." (PMID 37017565, 2023).
breast carcinoma (62 papers, 2014 to 2025). "Specifically, in breast cancer, SF3B1 mutations induce a recurrent pattern of aberrant splicing, leading to activation of AKT and NF-κB, enhanced cell migration, and tumorigenesis in mammary epithelial and breast cancer cells." (PMID 40694421, 2025). "Under the conditional elimination of primary site-derived breast carcinoma cells, lung malignant cells expressing the mutated SF3B1 splice variant dominate the newly created tumors." (PMID 37254190, 2023). "In breast cancer, mutations in SF3B1 are more frequently observed in the metastatic setting, and its potential role in the regulation of protein degradation or metabolism is known." (PMID 34439272, 2021). "For example, SF3B1 was identified as a breast cancer driver gene, mutated in 20% of uveal melanoma tumors and SF3B1 mutations have been related to adverse clinical outcome in CLL." (PMID 33648524, 2021). "In breast cancer, overexpressed SF3B1 is associated with lymph node metastasis and SF3B1 knockdown inhibits breast cancer cell proliferation, invasion, and migration via aberrant splicing." (PMID 33932092, 2021). "In breast cancer, SF3B1 mutations induce missplicing‐associated downregulation of the serine synthesis pathway enzyme PHGDH and decrease mitochondrial respiration." (PMID 33932092, 2021). "ABCC5 is described as differentially spliced in SF3B1 mutated breast cancer, and MRPS21 is described as a gene, whose upregulation is associated with poor response to azacytidine in MDS and related cancers." (PMID 34499147, 2021). "In breast cancer, SF3B1 mutations are associated with poor prognosis in PR-negative and luminal B subgroups." (PMID 33333932, 2020). "This is in accordance with previous work reporting the SF3B1 mutation is predominantly found in the luminal A subtype of breast cancer, a subgroup known to have a relatively better outcome than other breast cancer patients." (PMID 31841262, 2020). "Few studies and our own analysis demonstrate that the splice factors U2AF1, SRSF2 and SF3B1 are often mutated in myelodysplastic syndromes, but also in solid cancers amongst which breast cancer." (PMID 31666932, 2019). "Accordingly, our splice factor mutation analysis of breast cancer tumors from the COSMIC database revealed frequently mutated spliceosome genes amongst which SF3B1." (PMID 31666932, 2019). "For the luminal breast cancer subtype, mutations in SF3B1 were found to be possible driver mutations." (PMID 31666932, 2019). "The most common spliceosomal gene mutation is SF3B1, which is associated with ER+ breast cancer and seen in around 3% of ER+ tumours, whereas mutations in SON and SAP130 appear to be associated with ER− disease." (PMID 29848666, 2018). "The most common SF3B1 mutation in breast cancer is the K700E variant akin to CLL but K666Q and K666E are also observed, albeit at much lower frequencies." (PMID 29848666, 2018). "We performed this study to comprehensively investigate the association between SF3B1 mutations and prognoses in breast cancer patients." (PMID 29383138, 2017). "In breast cancer, in particular, SF3B1 mutations were significantly associated with ER-positive disease, AKT1 mutations, and distinct copy number alterations." (PMID 28198434, 2017). "In conclusion, our analysis of TCGA revealed that SF3B1 mutations are frequently found in breast cancer patients, and that they are poor prognostic indicators in PR-negative and luminal B breast cancer patients." (PMID 29383138, 2017). "The purpose of this study was to explore the relationship between SF3B1 mutations and the prognoses of patients with breast cancer." (PMID 29383138, 2017). "Age at diagnosis and estrogen receptor (ER) status were associated with SF3B1 mutations in all breast cancers (P < 0.01) and in luminal B and PR-negative subgroups (P < 0.01)." (PMID 29383138, 2017).
breast carcinoma (continued). "SF3B1 mutations were found to be significantly associated with the age at diagnosis and/or ER status in PR-negative and luminal B breast cancer patients." (PMID 29383138, 2017). "Receiver operating characteristic (ROC) curves were generated for all patients with breast cancer to identify the sensitivity and specificity of age at diagnosis and ER status in predicting SF3B1 mutation." (PMID 29383138, 2017). "SF3B1 mutations were evaluated as prognostic factors in all breast cancer patients and specific subgroups through Cox regression and Kaplan-Meier analyses." (PMID 29383138, 2017). "In terms of mutation frequency among different carcinomas, we found that the SF3B1 mutation ranged between 5% and 10% in breast cancer." (PMID 29383138, 2017). "Mutation of SF3B1 in spliceosomal component genes was the most common in breast cancers, and was detected in approximately 1.8% of cases." (PMID 29383138, 2017). "We focused on the breast cancer samples that had p.K700E mutation in the cohort, ranking them based on SF3B1 mRNA expression level; we found positive correlation (r = 0.48) between the pDM expression and sample-level splicing entropy." (PMID 27272679, 2016). "Another missense mutation in SF3B1 (Chr2:198266834:T > C; p.K700E), detected in eight breast cancer samples, also carried the signatures of pDM." (PMID 27272679, 2016). "Given the apparent association of SF3B1 mutations with mucinous carcinomas of the breast, we screened additional cohorts of ER-positive special histological types of breast cancer for SF3B1 K700E mutations." (PMID 25424858, 2015). "Additional profiling of hotspot mutations in a panel of special histological subtypes of breast cancer showed that 16% and 6% of papillary and mucinous carcinomas of the breast harboured the SF3B1 K700E mutation." (PMID 25424858, 2015). "This analysis revealed that mutations in spliceosomal component genes occurred in 5.6% of unselected breast cancers, including hotspot mutations in the SF3B1 gene, which were found in 1.8% of unselected breast cancers." (PMID 25424858, 2015). "Despite the modest sample size, our data align with global SF3B1 mutation rates in breast cancer." (PMID 41294844, 2025). "Mutations of SF3B1-encoding proteins involved in RNA splicing may be a driving factor and novel therapeutic target in breast cancers." (PMID 36466711, 2022). "Transcriptome analysis of SF3B1WT and SR3B1MUT tumors from CLL, UVM, and breast cancer patients allowed the identification of splicing alterations associated with SF3B1 hotspot mutations and revealed that SF3B1MUT stimulates the usage of cryptic 3′ splice sites by recognizing a cryptic BPS." (PMID 35053445, 2022). "SF3B1 gained importance due to many functionally deleterious mutations found in various cancer types [i.e., myelodysplastic syndrome /breast cancer /prolactinomas /uveal melanoma /pancreatic ductal adenocarcinoma], which are associated with patient poor-prognosis/survival." (PMID 35086552, 2022). "Indeed, SF3B1 is the most commonly mutated spliceosomal component gene in breast cancer, and mutations affecting this gene are significantly associated with ER-positive disease." (PMID 32905346, 2020). "There is increasing evidence that spliceosomal component genes themselves are dysregulated in breast cancer, through mutations in SF3B1 that are also observed in metastatic disease and upregulation of SF3B3 and SRSF1 in particular, which are associated with resistance to endocrine therapy." (PMID 29848666, 2018). "Among 11 common prognostic factors investigated, univariate analysis showed that age, ER status, PR status, menopausal state, PAM50 and claudin-low subtype, and breast cancer type were significantly associated with SF3B1 mutation in all breast cancer patients (P < 0.01)." (PMID 29383138, 2017). "In our study, we further analyzed the clinic value of SF3B1 mutations in breast cancer patents." (PMID 29383138, 2017).
breast carcinoma (continued). "As demonstrated by spliceostatin A, the SF3b complex may be a novel therapeutic target for breast cancer patients with SF3B1 mutations." (PMID 29383138, 2017). "We have demonstrated that SF3B1 K700E mutations are more frequently found in some special histological types of breast cancer and have provided direct evidence that these are associated with consistent differential splicing patterns in breast cancer." (PMID 25424858, 2015). "Albeit rare, SF3B1 mutations result in alternative splicing events, and may constitute drivers and a novel therapeutic target in a subset of breast cancers." (PMID 25424858, 2015). "Moreover, we demonstrate that SF3B1 is the most commonly mutated spliceosomal component gene in breast cancer and that mutations affecting this gene are significantly associated with ER-positive disease." (PMID 25424858, 2015). "Notably, hotspot SF3B1 mutations were linked to poor outcomes in breast cancer patients." (PMID 41294844, 2025). "SF3B1 mutations have been identified in uveal melanoma (15%–29%), cutaneous melanoma (1%), pleural mesothelioma (2%), pancreatic ductal adenocarcinoma (3%), breast cancer (2%–4%), and prostate cancer (1.1%), while U2AF35 mutations were found in lung adenocarcinoma (3%) and prostate cancer (0.5%)." (PMID 32106418, 2020). "Interestingly, we identified SF3B1 K700E mutations at higher frequencies in some rarer histological subtypes of breast cancer including 16% of papillary carcinomas and 8% of mucinous carcinomas of the breast, suggesting they may underpin their biology." (PMID 29848666, 2018). "SF3B1 mutations may therefore be a novel therapeutic target for breast cancer patients." (PMID 29383138, 2017). "One of the Zeb1 interactors is the splicing factor SF3B1, which is overexpressed in breast cancer tissue compared to normal tissue." (PMID 37372954, 2023). "SF3B1 silencing in breast cancer cell lines inhibited aberrant splicing, reducing cell proliferation, migration, and invasion, suggesting a potential antineoplastic role for SF3B1 inhibitors." (PMID 38067388, 2023). "Mutations in some RNA splicing factors, such as SF3B1, SRSF2, and U2AF1, have been found to be involved in the pathogenesis of cancers, such as lung cancer, breast cancer, and pancreatic cancers." (PMID 36371223, 2022). "SF3B1 is the most commonly mutated splicing gene in MDS and can also be mutated in solid tumors such as breast cancer, melanoma, and others." (PMID 36040792, 2022). "SF3B1 has been reported to be overexpressed in prostate cancer, hepatocellular carcinoma, and breast cancer." (PMID 33932092, 2021). "In the present study, we demonstrated that targeting SF3B1 using pladienolide B strongly affected breast cancer proliferation by increasing sororin alternative splicing and affecting the nuclear phenotype similar to our candidate splicing factor knockdown." (PMID 33648524, 2021). "These splicing inhibitors have been evaluated in SF3B1 mutant breast cancer cell lines and cells of MDS patients." (PMID 33333932, 2020). "Although less frequently than SF3B1, the mutations of SF3B3 and SF3B4, other components of the SF3b complex, are also observed in breast cancers (0.2% each)." (PMID 32106418, 2020). "In another study, it has been shown that mutations affecting SF3B1 gene caused alternative splicing of key genes such as UQCC, F8, ABCC5, and GUSBP11 in ER (estrogen receptor)-positive breast cancer." (PMID 32354150, 2020). "The melanoma cell line COLO829 and the breast cancer cell line HCC38, which were reported to have SF3B1 missense mutations in exons 12 and 15, respectively, are also sensitive to FR." (PMID 30719229, 2019). "Aside from alterations in spliceosomal component genes themselves, there is emerging evidence that oncogene activation imparts a functional dependency on SF3B1 and other components in breast cancer." (PMID 29848666, 2018).